DNMT1 (DNA methyltransferase 1)
Diseases named in the same sentence as DNMT1 in open-access papers (continued):
Sharing a sentence is not in itself a finding about the gene and the disease.
lung carcinoma (continued). "For example, DNMT1 interacted with NEAT1 to regulate cytotoxic T-cell infiltration in lung cancer via inhibition of the cGAS/STING pathway." (PMID 36226184, 2022). "MiRNA-21, which is recognized as a potential serum biomarker during epigenetic therapy in MDS, is also an up-regulator of EZH2 in human lung cancer stem cells, whereas miRNA-148a has recently been recognized as a down-regulator of DNMT1 in AML cells." (PMID 36555712, 2022). "Our NGS gene expression profile also showed that DNMT1 was increased in E2-treated A549 lung cancer cells." (PMID 35589688, 2022). "For example, Ser154, Ser515, and Ser714 of DNMT1 are phosphorylated in HEK293T cells, Ser127, Ser143, and Ser714 of DNMT1 are found in Jurkat cells, and Ser143 of DNMT1 is in lung cancer cells." (PMID 35659740, 2022). "Suppression of SPP1 expression, either through siRNA or DNMT1 overexpression, is a potentially novel approach to inhibit the progression of lung cancer." (PMID 33996808, 2021). "DNMT1/3A/3B were positively related with PLK1/4 in lung cancer subtypes, except the correlation between DNMT3A and PLK1 without significance in lung squamous cell carcinoma." (PMID 34080290, 2021). "G9a was reported to bind DNMT1 and regulate lung cancer stemness via maintaining DNA methylation of multiple lung cancer stem cell genes." (PMID 34069116, 2021). "In lung cancer, p65 is known to directly recruit DNMT1 to chromatin to enhance the methylation of the BRMS1 promoter; thus, acting as a transcriptional suppressor." (PMID 34749775, 2021). "The enhancement of DNA methylation on gene promoters by tobacco exposure or nicotine treatment by activating DNA methyltransferase 1 (DNMT1) has been reported to cause abnormal target gene expression in bronchial epithelial cells and lung cancer cells." (PMID 33335306, 2021). "The elevated expression of DNMT1 has been reported in colon adenocarcinomas, hepatocarcinomas, and lung cancer." (PMID 33959155, 2021). "This study reported that miR-29a and miR-185 were downregulated in IPF and lung cancer, but their targets, collagen Type-I and DNA methyltransferase-1, were upregulated." (PMID 34831059, 2021). "For instance, lncRNA HOXA11-AS was highly expressed in lung cancer, and its overexpression facilitated the proliferation and metastasis of lung cancer cells via miR-148a-3p/DNMT1 axis." (PMID 33968966, 2021). "In gastric and lung cancer Linc00337 seems to decrease the transcription of target genes and bind to DNMT1 or EZH2." (PMID 33054826, 2020). "Our findings demonstrated that NEAT1 interacted with DNMT1 to regulate cytotoxic T cell infiltration in lung cancer via inhibition of cGAS/STING pathway." (PMID 32296457, 2020). "RNA immunoprecipitation assay confirmed that NEAT1 was able to bind to DNMT1 in both lung cancer cells." (PMID 32296457, 2020). "The cellular expression of MEG3 was reported to be regulated by DNA methyltransferase (DNMT) 1 in lung cancer cells and in glioma cells, as well as by both DNMT1 and 3b in hepatocellular cancer cells." (PMID 30818784, 2019).
lung carcinoma (continued). "We show that gallic acid (GA) changes the methylome of lung cancer and pre-malignant oral cell lines and markedly reduces both nuclear and cytoplasmic DNMT1 and DNMT3B within 1 week." (PMID 29416619, 2018). "We found that DNMT1 expression was decreased in the lung tumor tissue of IL-32γ mice, and this effect was confirmed in the lung cancer cell lines." (PMID 29467412, 2018). "USP24 stabilizes p300 and β-TrCP to increase the levels of histone-3 acetylation and NF-κB, and decreases the levels of DNMT1 and IκB, thereby increasing IL-6 transcription in M2 macrophages and lung cancer cells, results in cancer malignancy finally." (PMID 30266897, 2018). "To further confirm the role that DNA methylation plays in CSTA gene expression, we knocked down DNMT1 (left) in 4 lung cancer cell lines, and found that down-regulation of DNMT1 led to a significantly increased CSTA expression in H23 and COLO677, but not H226." (PMID 29581829, 2018). "Here, the authors demonstrate that USP24 stabilizes p300 and β-TrCP to increase the levels of NF-κB and histone-3 acetylation, and decrease DNMT1 and IκB levels which promotes IL-6 expression in M2 macrophages and lung cancer cells." (PMID 30266897, 2018). "We here investigated an alternative strategy in the lung cancer therapy and aimed to estimate and compare its efficiency and side effects of knockdown of DNMT1 in vitro and in vivo." (PMID 28938637, 2017). "In this study, we provided an additional mechanistic evidence demonstrating that solamargine also affected the EP4 downstream effectors (DNMT1 and c‐Jun), thereby suppressing lung cancer cell growth." (PMID 27620163, 2017). "Recent study showed that activation of Rb protein causes decreased expression of DNMT1, allowing for increased MEG3 expression and decreased cancer cell growth in lung cancer cell." (PMID 29287592, 2017). "The expression of DNMT1 was also confirmed in normal lung epithelial cells and two lung cancer cell lines, A549 and H358 has higher expression of DNMT1 than BEAS-2B in mRNA and protein level." (PMID 28938637, 2017). "In human non‐small cell lung cancer, bELE inhibits cell proliferation through the downregulation of DNA methyltransferase 1 (DNMT1), and forced expression of DNMT1 reverses the inhibition effect." (PMID 28297578, 2017). "Overexpression of DNMT1 has been found in various cancer types including lung cancer and inhibition of DNMT1 suppressed growth and induced apoptosis of cancer cells through multiple signaling pathways and distinct mechanisms." (PMID 26362062, 2015). "Overall, the results above indicated that activation of ERK1/2 and AMPKα involved in the β-elemene-reduced DNMT1 protein and that expression of DNMT1 was required in the β-elemene-inhibited lung cancer cell growth." (PMID 25598321, 2015). "High intranuclear DNMT1 levels correlated significantly with smoking status and poor survival in 124 patients with lung cancer." (PMID 24130964, 2013). "Its reported ability to target DNMT1 and 3, resulting in global hypo-methylation and upregulation of tumor suppressor genes supports a pro-apoptotic role in lung cancer cells." (PMID 22952654, 2012). "DNMT1 overexpression was found in many types of cancers including lung cancers, particularly in patients who were smokers." (PMID 22174919, 2011). "The average positive rate of DNMT1 was significantly higher in 84 lung cancer tissues [(58.04 ±35.07)%] than that in corresponding normal lung tissues [(6.88±10.26)%](t=12.835, P < 0.001)." (PMID 20840813, 2010).
lung carcinoma (continued). "The over-expression of DNMT1 is an early indicator in the development of lung cancer, which occurs earlier than the methylation disturbance." (PMID 20119531, 2009). "Although the latest studies are concerned about the effect of demethylation on lung cancer, but one must be born in mind that down regulation of DNMT1 leads to a decrease in genomic instability." (PMID 20119531, 2009). "The hypermethylation of TSG is a common thing in lung cancer, and it is generally acknowledged that DNMT1 is correlated with hypermethylation in the TSG promoters, especially among smoking SCC patients." (PMID 20119531, 2009). "For example, it would have been desirable to have genotyped nsSNPs mapping to DNMT1 and DNMT3b, given previously published data implicating variation in these genes in development and prognosis of lung cancer." (PMID 17533396, 2007). "Similarly, another study reported that lncRNA NEAT1 interacts with DNMT1 to regulate cytotoxic T cell infiltration by inhibiting cGAS/STING pathway in lung cancer." (PMID 40308809, 2025). "In lung cancer cells, a reduction in miR-148a expression corresponds with an increase in DNMT1 levels, resulting in abnormal DNA methylation patterns, hypermethylation of specific tumor suppressor gene promoters, and subsequent gene silencing, which contributes to lung cancer progression." (PMID 41394878, 2025). "Recently, biguanides have been shown to modulate DNMT1/miR-152 expression in lung cancer." (PMID 38622665, 2024). "High expression of DNMT1 protein in serum may increase the pathogenesis of non-small-cell lung cancer and may play an important role in the early development of lung cancer." (PMID 38791306, 2024). "miR-148b directly controls DNMT1 and DNMT3b in lung cancer cells." (PMID 36959680, 2023). "Moreover, previous results have demonstrated that DNMT1 acts as a promoter of lung cancer, and the safety and feasibility of CRISPR/Cas9 gene-editing approaches in NSCLC have been verified." (PMID 36091786, 2022). "The results demonstrate that solamargine has a potent effect in inhibiting the expression of the DNMT1 protein and the proliferation of human lung cancer cells by decreasing the expression of the prostaglandin E2 (PGE2) receptor protein EP4 and activating ERK1/2 signaling." (PMID 34835969, 2021). "Solamargine, in this research, caused epigenetic changes and could be a novel strategy to inhibit lung cancer cell growth via precisely targeting EP4 downstream c-Jun through ERK1/2-mediated a decrease in DNMT1." (PMID 34835969, 2021). "G9a HMTase activity was linked to cancer stemness in lung carcinoma by maintaining oncogenic DNA methylation patterns via interaction with DNMT1, but not DNMT3A." (PMID 33323965, 2021). "Besides, reducing MEG3 expression, engendered by dysfunctional pRb‐DNMT1 signaling, was documented to boost multiplication of lung cancer cells." (PMID 32618397, 2020).
lung carcinoma (continued). "Having demonstrated that NEAT1 promoted growth and migration/invasion of lung cancer cells, we speculated whether blocking of DNMT1 was able to reverse the protumor effect of lncRNA NEAT1." (PMID 32296457, 2020). "Consistently, our bioinformatic analysis of published methylome profiles determined in human ES cells and in lung cancer cells revealed a strong correlation between the flanking preferences of DNMT1 with modulations of methylation patterns observed in the human cells." (PMID 32709850, 2020). "Mithramycin A, an antibiotic with potent antitumor activity, binds to sequences of GC-rich or CG-rich DNA and upregulates tumor suppressor genes’ expression by reducing the methylation of their promoters through binding and depleting the DNMT1 protein in lung cancer cells." (PMID 33312959, 2020). "For example, DNA methyl‐transferase 1 (DNMT1) was experimentally validated as a target of miR-148a in gastric cancer cells, miR-148b in lung cancer cells, and miR-152 in ovarian and liver cancer cells, in each of which overexpression of the miRNAs induced tumor suppressive effects." (PMID 32337535, 2020). "Since smoking is the predominant cause of lung cancers, we investigated whether further exposure of SCLC cells to the tobacco carcinogen, NNK, would affect DNMT1 levels, and indeed it did, especially after 48 h." (PMID 29559689, 2018). "Furthermore, our results suggested the critical role of DNMT1 in mediating the effect of solamargine on inhibition of lung cancer cell growth." (PMID 27620163, 2017). "In present study, we found up-regulated expression of DNMT1 in lung cancer tissues and cell lines." (PMID 28938637, 2017). "We believed that, as unfavourable tumour‐promoting role, DNMT1 could be a novel target in mediating the inhibitory effect of solamargine in lung cancer intervention." (PMID 27620163, 2017). "By demonstrating DBCCR1-dependent DNMT1 gene regulation in human cancer cell lines, we provide evidence to suggest DBCCR1 repression may serve as a molecular switch that stimulates up-regulation of DNMT1 in lung cancer." (PMID 28427182, 2017). "When DBCCR1 was genetically manipulated in a human lung cancer cell line, we found that DNMT1 expression was reciprocally modulated, implicating a more complex interaction of cancer-associated gene repressions with transcriptional up-regulation of DNA methylation." (PMID 28427182, 2017). "Our findings suggested that c‐Jun may be one of downstream effecters of EP4 and DNMT1 and that inhibition of c‐Jun was required to mediate the effect of solamargine on lung cancer cell growth." (PMID 27620163, 2017). "TC1, β-catenin, and DNMT1 can synergistically activate Wnt/β-catenin signaling in lung cancers." (PMID 28968956, 2017). "Reports demonstrated that targeting DNMT1 may be of therapeutic benefit for patients with several malignancies including lung cancer 10–13." (PMID 25598321, 2015). "Our findings suggested that DNMT1 may act as a potential new target that mediated the anti-lung cancer properties of β-elemene." (PMID 25598321, 2015). "In addition to miR-29s, ectopic expression of miRNA-148a in lung cancer cell lines also results in a significant reduction in the expression of DNMT1." (PMID 25949795, 2014). "Importantly, DNMT1 overexpression in lung cancer patients who smoked continuously correlated with poor prognosis." (PMID 24130964, 2013). "The high expression of DNMT1 was positively correlated with adenocarcinoma histological type (r=0.365, P=0.001), poor differentiation (r=0.253, P=0.021) and lymph node metastasis (r=0.246, P=0.024) in lung cancer." (PMID 20840813, 2010). "The high expression of DNMT1 was correlated with the malignant phynotype of lung cancer." (PMID 20840813, 2010).
lung carcinoma (continued). "Their study suggested that the siRNA approach could be used to disrupt effectively DNMT1 activity and lung cancer cell growth." (PMID 20119531, 2009). "NNK has been reported to play a key role in induction of lung cancer through DNA damage, activating α7 nicotine acetylcholine receptor and several signaling pathways, regulation of gene expression through DNA‐methyltransferase 1 (DNMT1), and immune suppression." (PMID 41362702, 2025). "For instance, lncRNA HOTAIR has been shown to associate with DNMT1, DNMT3A, and DNMT3B, which are concentrated in the promoter regions of genes associated with tumor metastasis, resulting in hypermethylation of these genes and promoting the metastatic potential of lung cancer cells." (PMID 41394878, 2025). "Importantly, the authors found that STING silencing was associated with LKB1 loss also in KRAS WT lung cancers, and was especially robust when combined with elevated DNMT1 levels, suggesting that this mechanism is not purely limited to the KL cellular state." (PMID 38791897, 2024). "Mechanistically, tobacco-smoke carcinogens are likely to increase DNMT1 expression through disrupting pathways involved in DNMT1 ubiquitination and degradation; this results in de novo promoter hypermethylation of TSGs and, eventually, tumorigenesis in lung cancers." (PMID 35205708, 2022). "The results revealed that decrease in DNMT1 and histone deacetylase activities, that probably block epigenetically mediated gene silencing, might provide an emerging clinical strategy to help prevent lung cancer." (PMID 36091786, 2022). "Moreover, it was reported that transforming growth factor β1 (TGFβ1) induces decreased expression of DNA methyltransferase 1 (DNMT1) and PD-L1 promoter demethylation, which subsequently results in PD-L1 overexpression in lung cancer cells undergoing epithelial-mesenchymal transition (EMT)." (PMID 31258527, 2019). "Furthermore, increasing activity of DNA methylation driven by elevated DNMT1 expression in lung cancer could contribute to pathogenesis and progression of tumors through the CpG island hypermethylation of cancer suppressors." (PMID 28427182, 2017). "Thus, deregulation or inactivation of EZH2 and DNMT1 could be important drivers of development, progression of tumor, and may be of therapeutic benefit for patients with malignancies including lung cancer." (PMID 26362062, 2015). "DNMT1 accumulation and subsequent hypermethylation of the promoter of tumor suppressor genes may lead to tumorigenesis and provide an important link between tobacco smoking and lung cancer." (PMID 24130964, 2013). "DNMT1 may express coordinately with β-catenin in lung cancer." (PMID 20840813, 2010). "So, NEAT1, by interacting with DNMT1, inhibits the cGAS/STING pathway, thereby regulating cytotoxic T cell infiltration in lung cancer." (PMID 40387409, 2025). "This study revealed that NNK exposure enhances DNMT1 activity and consequently suppresses the transcription of RING1 in lung cancer cells." (PMID 41362702, 2025). "The development and progression of lung cancer involve the dysregulation of several molecular pathways, including those involving CIP2A, RING1, and DNMT1 proteins." (PMID 41362702, 2025).